CD4 (CD4 molecule)
Diseases named in the same sentence as CD4 in open-access papers (continued):
Sharing a sentence is not in itself a finding about the gene and the disease.
Stroke (continued). "CD8+ TRLs enter the ischemic brain early after stroke, preceding the infiltration by CD4+ Tregs." (PMID 35912857, 2022). "Among lymphocyte subsets, the percentage of CD4+ Tregs was a more sensitive biomarker to predict the prognosis of stroke and influence treatment strategies, and it had independent predictive ability for admission, discharge and neurological function at 3 months." (PMID 35789538, 2022). "In our study, we observed a significant increase in circulating CD4 + T-bet + T cells, expression of an involvement of Th1 response, in very early stages of cerebral ischemia which tended to increase during the first week after stroke onset." (PMID 36180482, 2022). "Furthermore, following stroke, IL-21 and its receptor are expressed in the CNS via brain infiltrating CD4+ T cells, and CNS IL-21 strongly contributes to CNS tissue damage." (PMID 36256663, 2022). "CD4+ T-cells also have a differential response to stroke in the aged brain." (PMID 34711943, 2022). "In the same sample, stroke due to large artery atherosclerosis was associated with higher CD4 count in the year prior to stroke, independent of CD4 nadir." (PMID 34239489, 2021). "The frequency of CD69+CD4+ T cells inversely correlated with stroke severity." (PMID 33205448, 2021). "However, compared to MCAO group, IPostC significantly decreased the percentage of CD4 T cells, CD4 Tem cells, cDC, and MoDM in the ischemic brain at day 1 and day 3 after stroke." (PMID 34094644, 2021). "This demonstrates that a B-lymphocyte response to stroke still occurs in CD4−/− and MHCII−/− mice." (PMID 32956832, 2021). "Deficiency in CD4 T cell subsets is associated with preeclampsia and may contribute to PP vascular disease, including internal carotid artery (ICA) stenosis and stroke." (PMID 34220551, 2021). "This suggests the application potential of a novel therapy using accessible humanized anti-PD-L1 antibodies to treat human stroke subjects and confirms that PD-1 is inversely correlated with the absolute amount of CD4+ T central memory (TCM) cells in ischaemic patients." (PMID 33461586, 2021). "IPostC induced protection is involved in downregulating P38 of CD4 T cell and Treg after stroke." (PMID 34094644, 2021). "They concluded that large artery atherosclerosis was the most frequent stroke mechanism in PLWH whose nadir CD4 count was less than 200 (which suggests cART start later in infection history) and whose CD4 count near the time of the stroke was higher (which suggests successful cART)." (PMID 34239489, 2021). "Interestingly, in CD4+ T cells, we identified two different IL-10+ subpopulations that peak at different timepoints following stroke." (PMID 34772416, 2021). "CD4+ T cell count slightly increases from day 1 to day 6 after stroke." (PMID 34335623, 2021). "Interestingly, under the physiological state, the pDCs had the ability to stimulate the CD4 T lymphocytes and Tregs proliferation, and the immunostimulatory capacity on the CD4 T lymphocytes and Tregs was strengthened under the pathological state of stroke." (PMID 32076400, 2020). "A recent study showed increased expression of soluble CD137 on CD4+ T cells in peripheral blood of patients following an episode of stroke compared to controls and may therefore be a potential therapeutic target." (PMID 32477327, 2020). "Nevertheless, CD4+ cells as well as B cells tended to be lower after experimental stroke." (PMID 33329318, 2020). "In addition, investigations of the lung immunity after stroke have shown a significant reduction of CD4+, CD8+ and B cells 24 h and 72 h after MCAo." (PMID 32481512, 2020). "Indeed, subsequent studies of blood CD4 T cells in CD200R1-KO mice showed a marked re-arrangement in TCRvβ usage at 1 week after stroke, with significantly higher frequency shifts in the subfamily member’s vβ8.1 and 8.2." (PMID 30777093, 2019). "Interestingly, selective expansion of memory CD4 T cells expressing TCRvβ 8.1/8.2 was found in KO mice after stroke." (PMID 30777093, 2019).
Stroke (continued). "Fittingly, a study of tMCAo stroke in mice, showed a significant autoimmune response to brain antigens at 4 days through 10 days after stroke, determined by an increase in autoreactive CD4+ and CD8+ T cells and CD19+ B cells, isolated from spleens and cervical lymph nodes." (PMID 31001280, 2019). "Thus, we analyzed the role and mechanism of hyperforin in the infiltration of CD4+ lymphocytes and Tregs to the ischemic hemisphere during stroke recovery." (PMID 31133816, 2019). "Next, we examined the expression of IFN-γ in the lung NK and CD4+ T cells after stroke." (PMID 31447768, 2019). "However, Treg depletion led to worse neurological outcomes and larger lesion sizes, suggesting that it is pro-inflammatory CD4+ T cells that contribute to poor outcomes in stroke." (PMID 31572381, 2019). "CD4+ and CD8+ T cells have been shown to contribute to the inflammatory response, brain injury, and subsequent neurological deficits associated with adult experimental stroke." (PMID 29615958, 2018). "However, CD4 deficits further resulted in higher arginase I protein levels at 5 h and 24 h, as well as 48 h after stroke, compared with WT mice." (PMID 32832192, 2018). "With regard to the elevated plasma sCD137 levels, we initially assumed that the increased sCD137 production may predominately result from the upregulated CD137 expression on CD4+ T cells of stroke patients." (PMID 29697202, 2018). "We found that high concentration of anti-CMV IgG was not an independent risk factor for stroke in contrast to low CD4+ count, prior history of stroke or TIA, and abdominal obesity." (PMID 30481210, 2018). "Our results preliminarily indicate that PD-1 may play an important role in CD4+ T cell dysfunction during the stroke process." (PMID 30013463, 2018). "Fox P3+CD25+CD4+ regulatory T cells (Tregs) are presumably involved in stroke-related events." (PMID 28373915, 2017). "Of interest, we found higher expression of IFN-γ in stroke mice, especially by CD4+ T cells." (PMID 29246244, 2017). "In our population, these parameters were not significant predictors of all‐cause mortality, but CMV (although not the Cd4/CD8 ratio) predicted cardiovascular mortality as well as death from MI or stroke in agreement with recent results." (PMID 26696322, 2016). "Nevertheless, it is conceivable that CD4+ D28 null subset of T-cells could be resistant to stroke-induced apoptosis." (PMID 25997053, 2015). "The authors argue that CD4+ T cell count on the day after stroke may emerge as a predictive marker for post-stroke infection." (PMID 24597828, 2014). "Also, CD80/CD28 interactions played a prominent regulatory role for the CD8+ T-cells and the PD-1/PD-L2 interactions were dominant in controlling the CD4+ T-cell responses in WT mice after stroke." (PMID 25157219, 2014). "Their observation is reinforced by our findings, indeed showing a loss of CD4+ T cells even within 6 hours after stroke onset, and a recovery of CD4+ T cell prevalence one week after the insult in the lack of infection." (PMID 24597828, 2014). "There is also evidence that regulatory T lymphocytes (Tregs; CD4+CD25+FoxP3+) may modulate the severity of stroke outcome, despite exerting acutely detrimental effects by promoting intravascular coagulation during reperfusion." (PMID 25477780, 2014). "Interestingly, the CD80/CD28 interactions appeared to play a prominent regulatory role for the CD8+ T-cells while the PD-1/PD-L2 interactions were dominant in controlling the CD4+ T-cell responses in WT mice, after stroke." (PMID 25157219, 2014). "Alternatively, Offner and colleagues suggest that SIID might be induced by increases in regulatory T cells (Tregs) after stroke while other T cell subsets, such as CD4+ and CD8+ T cells, as well as B cells were reduced." (PMID 23555048, 2013).
Stroke (continued). "Moreover, another study declared that FoxP3+CD4+ Tregs greatly augmented acute ischemic/reperfusion injury after stroke, and this detrimental effect persisted into the later period of infarct development in a DEREG mouse model." (PMID 23983771, 2013). "CD4+ TH1 cells may progress stroke through releasing proinflammatory cytokines, including IL-2, IL-12, IFN-γ, and TNF-α, whereas CD4+ TH2 cells may play a protective role through releasing anti-inflammatory cytokines such as IL-4, IL-5, IL-10, and IL-13." (PMID 23431245, 2013). "Some evidence depicts the unique role of FoxP3+CD25+CD4+ Tregs in stroke pathogenesis." (PMID 23983771, 2013). "Stroke in WT rats induced significant decreases in total numbers of splenocytes and absolute numbers of all measured immune-cell subsets, including T cells, CD4+ T cells, CD8+ T cells, Tregs, NK cells, B cells and monocytes." (PMID 23555048, 2013). "Therefore, the principle issue behind a therapeutic intervention based on FoxP3+CD25+CD4+ Treg modulation is identifying the precise roles of FoxP3+CD25+CD4+ Tregs at specific stages of stroke." (PMID 23983771, 2013). "The increased presence of FoxP3+CD4+ Tregs might participate in stroke-induced immunosuppression on the peripheral immune system." (PMID 23983771, 2013). "Specifically, FoxP3+CD25+CD4+ Tregs acquired notable attention because of their role in a variety of central nervous system (CNS) and autoimmune pathologies, such as multiple sclerosis (MS), stroke, and glioblastomas." (PMID 23983771, 2013). "CD4+CD25+FoxP3+ naturally occurring regulatory T cells have been shown to reduce the impact of stroke and may have similar protective roles in the injured brain." (PMID 22152221, 2011). "In addition, we and others have described several immunological markers including CD4+ T-cell counts, serum IL-6 levels, and TNF-α release by macrophages that are associated with the occurrence of infection in stroke patients." (PMID 20090932, 2010). "This shows that in stroke CD4+ T-cells in the peripheral blood become activated." (PMID 20090932, 2010). "Significantly, activated T lymphocytes, particularly the CD4+ and CD8+ T cell populations, have been associated with the instability and rupture of plaques, which are critical contributors to acute cardiovascular events such as myocardial infarction and stroke." (PMID 40070840, 2025). "Among them, CD4+ T cell activation has been described by several groups within the first weeks after stroke, but it has remained unknown for how long such activation lasts in patients, which pathways could be of importance for chronic activation, and if such activation also applies for CD8+ T cells." (PMID 41373643, 2025). "However, considering post-stroke changes in the proportion of T cells, with a predominance of CD4+ T cells, especially the neuroprotective type of CD4+ T cells—Th2 type our findings may confirm the potential benefits of this phenomenon." (PMID 40342517, 2025). "However, considering that CD4+ T-cell subsets are likely to change with age, the change in CD4+ T-cell subset and its comparison between stroke patients and healthy controls as well as its correlation with cognition decline in healthy controls should be explored in the future." (PMID 38511768, 2024). "However, few studies have indicated the effect of ATG5 on CD4+ T-cell differentiation in stroke." (PMID 38511768, 2024). "Previous studies have also found associations between the level of CD4+ T cells and disease severity in MS, PD, stroke, AD, and other neurological diseases, so the count of CD4+ T cells altered in the periphery or CNS may be an effective index for monitoring the disease process for RIBI patients." (PMID 38499993, 2024). "Therefore, the study of CD4+ T cells and its regulators is of great significance in improving the mental health and cognitive function of stroke patients, which may further benefit their clinical prognosis." (PMID 37703110, 2023).
Stroke (continued). "Moreover, IL-17A+ T lymphocytes were detected in the post-mortem tissue of patients that died shortly after their stroke and IL-21-producing CD4+ T cells, potentially Th17, Tfh, or Th9 cells, were found surrounding the infarcted tissue area in post-mortem tissue of patients with acute stroke." (PMID 33173502, 2020). "We checked whether this imbalance in favor of CD8 T cells instead of CD4 T cells could have occurred locally in the cerebral vasculature of stroke patients by comparing blood from the middle cerebral artery obtained during a mechanical thrombectomy therapy with venipuncture blood of stroke patients." (PMID 32719588, 2020). "Evidences have shown that a second peak of infiltration of CD4+ lymphocytes to the ischemic hemisphere occurs around day 14 and persists until day 30 after stroke, and a strong accumulation and proliferation of Tregs in the ischemic hemisphere was observed for up to 30 days after stroke." (PMID 31133816, 2019). "However, whether CD4+ T-cell subpopulations exert effects on long-term stroke outcome through modulating post-stroke neuroangiogenesis remain unclear." (PMID 31133816, 2019). "CD4+ T cells produce pro-inflammatory cytokines, such as interferon (IFN)-γ, and CD8+ T cells secrete perforin/granzymes, all of which could cause neuronal death and worsen stroke outcomes." (PMID 30131754, 2018). "Furthermore, there may be differential effects of CD4+ T cell subsets on stroke outcome, such as exacerbation by Th1 cells and amelioration by Th2 cells of brain infarct development and functional deficit." (PMID 25477780, 2014). "The conflicting reports of CD4+ Tregs and stroke thus far indicate that there is still much unknown about the regulation of the immune response after stroke and even less known about Treg response to stroke in older subjects." (PMID 25309326, 2014). "Whether FoxP3+CD25+CD4+ Tregs are friends or foes in stroke, however, remains unclear." (PMID 23983771, 2013). "Lack of CD4+ T cells is associated with decreased lesion size after stroke." (PMID 23874591, 2013). "Considering the absence of other specific strategies or drugs for patients with stroke, modulating the quantity and function of FoxP3+CD25+CD4+ Tregs may be potential, novel avenues for developing new therapeutics that improve neurological outcomes after stroke." (PMID 23983771, 2013). "In addition, significant differences between male and female stroke patients in the frequency and suppressive effects of FoxP3+CD25+CD4+ Tregs were demonstrated in this study, but the underlying reasons for these observed differences are unknown." (PMID 23983771, 2013). "Importantly, FoxP3+CD25+CD4+ Treg-mediated immunosuppression could be protective or harmful at different stages of stroke." (PMID 23983771, 2013). "Moreover, because evidence acquired from animal experiments is often difficult to transfer into clinical study, more attention should be paid to the translational value between basic research and clinical trials in the investigation of FoxP3+CD25+CD4+ Tregs following stroke." (PMID 23983771, 2013). "In whole blood from stroke patients, the activation markers CD25, CTLA-4, and PD-L1 were quantified on CD4+ or CD8+ T cells at 3 days (t1), 1 month (t2), and 3 months (t3) post stroke and compared to old as well as young controls for age effects." (PMID 41373643, 2025). "In the acute post-stroke phase (t1), CD25 expression was significantly increased on both CD4+ and CD8+ T cells and only declined at t3." (PMID 41373643, 2025). "The experimental stroke model showed infiltration of CD8+ T cells in an ischemic area within 3 h since vessel occlusion and CD4+ T cells during the first 24 h." (PMID 40342517, 2025). "T cell subpopulations (CD4+, CD8+, DNT) and their activation (CD25, CD57, CTLA-4 (CD152) and PD-L1 (CD274)) were analysed in peripheral blood from stroke patients and controls by flow cytometry." (PMID 41373643, 2025).
Stroke (continued). "This indicates that a higher CD4+/CD8+ ratio correlated with better clinical status during the acute and subacute phases of stroke." (PMID 40342517, 2025). "Conversely, increased CD4 + and CD8 + T lymphocytes can worsen neurological dysfunction in elderly mice post-stroke." (PMID 40303468, 2025). "Having undergone stroke induction and PNU treatment, we harvested the draining lymph nodes of the brain, as well as the spleen, and quantified inflammatory CD4 T-cells using flow cytometry." (PMID 40012683, 2025). "Case Control Study seeking to determine by peripheral blood samples if patients that experience an increase in anti inflammatory Treg cells (CD4+, CD25, +FoxP3+, “brain” Treg) after stroke have improved clinical outcomes. // Recruiting." (PMID 40356948, 2025). "A higher CD4+/CD8+ ratio correlated with better clinical status in the acute and subacute phases of stroke, suggesting a detrimental effect of CD8+ T cells and a beneficial effect of CD4+ T cells already at the early stage of ischemia." (PMID 40342517, 2025). "Flow cytometry analysis revealed that the expression of P2X7 was mainly expressed in CD4+and CD8+T cells among the infiltrated lymphocytes in stroke lesions of the mice." (PMID 40948793, 2025). "Other research revealed infiltration of CD4+ and CD8+ T cells on day 3, day 5, or even 7 weeks after stroke onset." (PMID 40342517, 2025). "Flow cytometry analysis revealed that before treatment, the proportions of both CD4+ GZMK+ and CD8+ GZMK+ T cells were greater in the PBMCs of AIS patients than in those of non-stroke controls." (PMID 40659887, 2025). "Our results demonstrate significantly elevated P2X7 expression in CD4+T cells and CD8+T cells within stroke lesions." (PMID 40948793, 2025). "Among T cells, both CD4+ and CD8+T cells have been documented, and recent research suggests that T cells also impact brain damage triggered by strokes by infiltrating the ischemic brain." (PMID 38334672, 2024). "In the current study, we explored the alteration of CD4 + CD25 + CD127 low Treg, nTreg (CD4 + CD25 + CD127 low CD45RA+) and mTreg (CD4 + CD25 + CD127 low CD45RO+) in AIS and investigated their role in stroke outcome prediction." (PMID 36909948, 2023). "Young male mice show a greater increase in CD4+T cells and expression of the VLA-4 adhesion molecule in the spleen than female mice do following an experimental stroke." (PMID 36793730, 2023). "It has been reported that CD4+ or CD8+ T lymphocytes and B cells increase within 4 days after stroke." (PMID 36685518, 2022). "To test whether microglial phenotypes can be specifically skewed by the CD4+ T cell subsets of functionally opposing THELPER cell subpopulations, we differentiated TH1 and TREG in vitro and tested whether these THELPER cells can reprogram the stroke-associated microglia." (PMID 36512388, 2022). "This provides a mechanistic framework for the discovery of autoreactive CD4+ and CD8+ T lymphocytes, as have been found in a mouse model of stroke, potentiating neuronal damage in stroke through autoimmune inflammation." (PMID 35453590, 2022). "While this does not establish causality or mechanisms, these observations suggest that CD4+ and CD8+ cells might play opposing roles in histological and behavioural recovery, possibly because infarct size responds to mechanisms protecting the penumbra early after stroke." (PMID 35910379, 2022). "Using flow cytometry, we analyzed the percentage of CD4 + T-bet + T cells and CD4 + GATA3 + T cells from peripheral blood of ATHS and CES patients (2,4 and 7 days after stroke onset)." (PMID 36180482, 2022). "In contrast with these few positive effects on post-stroke histological and behavioural improvement, fingolimod robustly reduced the frequencies of lymphocyte populations (CD3+, CD4+) in blood and various lymphoid tissues." (PMID 35910379, 2022). "Regarding CNS antigens, autoreactive CD4 and CD8 T cells, and CD19 B cells appear as early as 4 days after stroke onset." (PMID 36446955, 2022).